BRAF (B-Raf proto-oncogene, serine/threonine kinase)
Diseases named in the same sentence as BRAF in open-access papers (continued):
Sharing a sentence is not in itself a finding about the gene and the disease.
melanoma (continued). "MLPA was conducted to detect chromosomal alterations and Sanger sequencing used to identify point mutations in candidate melanoma driver genes (BRAF, NRAS, KRAS, GNA11, GNAQ), and other genes implicated in melanoma prognosis (EIF1AX, SF3B1)." (PMID 30558566, 2018). "The development of a small molecule inhibitor that selectively targets the BRAF V600E mutation, vemurafenib (PLX4032), resulted in regression of BRAF mutant advanced melanoma." (PMID 30598662, 2018). "Melanoma patients with BRAF or NRAS mutant tumours had an increased risk compared to patients with BRAF/NRAS wild-type tumours of developing disease recurrence following a tumour-negative SLNB." (PMID 29755118, 2018). "Here we show a complete absence of somatic BRAF mutations (SNVs, CNVs, or translocations encompassing the BRAF locus) in canine malignant melanoma in keeping with prior studies." (PMID 30188888, 2018). "Subsequently, it has been demonstrated that raising ROS levels in BRAFV600E‐transformed melanoma cells by inhibiting BRAF or MEK rendered them susceptible to cell death induction." (PMID 29624862, 2018). "Among sensitive cell lines, Colo201, Colo205, HT29, and LS174T had a BRAF mutation that is known to improve the antitumor effect of a MEK inhibitor in melanoma with a BRAF mutation." (PMID 29896883, 2018). "Further, they revealed that loss of RhoB expression in metastatic melanoma tissues is correlated with an increase in progression-free survival of BRAF-mutant patients that were treated with vemurafenib." (PMID 29385717, 2018). "In particular, inactivating NF1 mutations are present in 46% of melanomas expressing wild-type BRAF and RAS and are more commonly observed in chronically sun-exposed skin, desmoplastic melanomas." (PMID 29534457, 2018). "BRAF inhibitors have demonstrated impressive clinical activity in patients with advanced melanoma that contains the activating BRAF V600 mutations." (PMID 29879227, 2018). "PTEN, the most frequently mutated gene in melanoma after BRAF and NRAS, promotes cell survival through sustained activation of the PI3K signaling pathways." (PMID 29946532, 2018). "BRAF mutations have been detected in 7% of all cancers and in 66% of melanomas and 12% of colorectal cancers." (PMID 29565994, 2018). "This cluster is an unusual tumor group, as it was also associated with 52% tumors on the limbs (a good prognostic factor for melanoma), high BRAF driver mutation status (55%), yet a high frequency of tumor ulceration (38%)." (PMID 29664013, 2018). "Somatic mutations of the BRAF gene, causing constitutive activation of BRAF, have been found in various types of human cancers such as malignant melanoma, and colorectal cancer." (PMID 29879227, 2018). "Given the regulatory role of ERK signaling on RSK/YB-1 axis and its importance in BRAF mutated melanoma, we examined the effect of fisetin on ERK phosphorylation." (PMID 30356079, 2018). "In August 2011, the US Agency of Food and Drug Administration (FDA) approved Vemurafenib, a BRAF inhibitor (BRAFi), for the treatment of metastatic or unresectable melanoma with BRAF V600E mutation." (PMID 29541007, 2018). "Approximately one-half of advanced (unresectable or metastatic) melanomas harbor a mutation in the BRAF gene, with V600E being the most common mutation." (PMID 29148538, 2018). "Our recent data indicate that the acquisition of BRAF resistance in BRAF-mutated metastatic melanoma cells is accompanied by a significant increase of intracellular NAMPT (iNAMPT), which becomes the master regulator of NAD biosynthesis." (PMID 29721178, 2018). "MAP kinase inhibitor (MAPKi) therapy for BRAF mutated melanoma is characterized by high response rates but development of drug resistance within a median progression-free survival (PFS) of 9–12 months." (PMID 29541007, 2018). "Seventy-four patients were included: 33 (44.6%) with wild-type-BRAF melanoma and 41 (55.4%) with BRAF-V600-mutated melanoma." (PMID 29970025, 2018).
melanoma (continued). "The BRAF Val600Glu (V600E) mutation were commonly seen in BRAF mutations that had been mainly found approximately 90% of melanoma." (PMID 30680072, 2018). "Therapies that can overcome the resistance to inhibitors of the mutated BRAF protein kinase in melanoma are urgently needed." (PMID 30100999, 2018). "This mutational landscape resembles that seen in BRAF wild-type and sun-shielded human melanoma subtypes." (PMID 30188888, 2018). "Inhibition of mutant BRAF in melanoma caused an increase in ROS production, which facilitated cell killing." (PMID 29624862, 2018). "Not surprisingly, the S210L mutation in APT1 is observed at a much lower frequency compared to well-established oncogenes frequently mutated in melanoma, such as BRAF or NRAS." (PMID 29648538, 2018). "It is also approved for the treatment for melanoma patients harboring a BRAF V600E mutation, following treatment with a BRAF inhibitor." (PMID 30547012, 2018). "The results showed that SK-MEL-2 cells have a lower ABCB5 expression than the other three melanoma cell lines with BRAF mutation." (PMID 29929490, 2018). "BRAF mutations have been identified in a wide range of malignancies including 10% of colorectal carcinoma, and 50% of malignant melanomas." (PMID 30680072, 2018). "For patients with BRAF wild-type melanoma or those patients with BRAF mutations showing tumour progression after targeted therapy, immunotherapy (i.e. ipilimumab, nivolumab or pembrolizumab) is the standard treatment prior to chemotherapy." (PMID 30181812, 2018). "Spliceostatin A and its analog meayamycin B target splicing factor SF3B1 and inhibit formation of the p61 BRAF V600E splice variant, which in turn re-sensitizes therapy-resistant melanomas to vemurafenib as demonstrated in both in vitro and in vivo models." (PMID 30463359, 2018). "Overall, our data are in agreement with literature data showing that BRAF is mutated in about 50% of melanomas and that NRAS is the second most frequently mutated gene." (PMID 30181807, 2018). "In melanoma, BRAF mutation is a central driver in cancer and has led to the evaluation of BRAF inhibitors being evaluated in clinical trials." (PMID 30150674, 2018). "Early observations demonstrated a link between MAPK signaling and the expression of melanoma-associated antigens, with subsequent data revealing brisk infiltration of tumors with T lymphocytes in the setting of treatment with BRAF inhibitor-based therapy." (PMID 29780391, 2018). "Dabrafenib and vemurafenib are potent kinase inhibitors of BRAF V600E-mutated melanoma cells, with substantial activity in BRAF-mutated melanoma BM." (PMID 29881714, 2018). "Specifically, we pursued supervised analyses of genetic networks by stratifying melanoma cell lines into groups defined by BRAF and/or KRAS mutation status and then evaluating differences in the overall network structure (i.e., relationships between genes)." (PMID 30042785, 2018). "More than 50% of melanomas are characterized by mutations in the BRAF gene, which constitutively activates the downstream kinase MEK/MAPK and promotes melanogenesis." (PMID 29661909, 2018). "In preclinical models, ribociclib also showed some activity in melanomas with activating mutations of BRAF or NRAS." (PMID 30631751, 2018). "Predictably, the resulting list featured well-documented melanoma drivers, such as known hotspot mutations in BRAF, NRAS, RAC1 and IDH14,11,12, confirming the validity of our strategy." (PMID 29330521, 2018). "Clinically, BRAF or NRAS-mutant melanoma patients whose tumors have TERT promoter mutations have poor overall survival compared to patients with tumors with a non-mutated TERT promoter." (PMID 29695835, 2018).
melanoma (continued). "Considering the total primary melanomas, we observed that BRAF mutation was concomitant in 19 out of 76 (25%) of samples with TERT promoter mutations and in 41 out of 62 (66%) with p16 loss of expression." (PMID 29464027, 2018). "Efficacy of molecular-targeted medicine for cancers with driver oncogenes, such as HER-2 amplification in breast cancer, EGFR mutation and ALK-rearrangement in NSCLC, and BRAF mutation in malignant melanoma, is found to be very high." (PMID 30443294, 2018). "Targeted therapy against BRAF mutation represents one of the most significant advances in the treatment of melanoma." (PMID 30100999, 2018). "The BRAF mutation constitutes a potential target for new anti-melanoma treatments, and the BRAF inhibitors vemurafenib and dabrafenib have demonstrated an improvement in both overall survival and progression-free survival." (PMID 29743521, 2018). "To assess the precise contribution of PI3K/AKT activity in BRAF/MEK inhibitor resistance, we selected gain-of-function PIK3CAH1047R and AKT3E17K mutations, both identified in melanoma and associated with BRAF inhibitor resistance." (PMID 30237495, 2018). "Since resistance to BRAF/MEK inhibitors is seen in the majority of melanoma patients, there is an immediate need to assess the underlying biology that mediates resistance and to identify new targets for combinatorial therapeutic approaches." (PMID 29315345, 2018). "Cellular senescence has been shown to prevent the malignant transformation of BRAFV600E benign naevi and it is implicated in melanoma cell response to BRAF inhibition, as well." (PMID 29682188, 2018). "In human xenograft models, cobimetinib decreased tumor growth of colon and melanoma tumors containing BRAF mutations." (PMID 29455659, 2018). "HiGom exhibited greater anti-proliferative activity against a range of BRAF-mutated melanoma cell lines in vitro as well as lower cytotoxicity to NFF cells, making it a better candidate for development of an anti-melanoma drug." (PMID 30068931, 2018). "Although occurring exclusively, mutation of either RAS or BRAF is commonly found in colorectal, thyroid, and ovarian cancers and melanoma which suggests that deregulation of the MAPK pathway at either level confers a selective advantage for these cancer types." (PMID 30598662, 2018). "An example of such a case is Vemurafenib, targeting BRAF V600 mutations in different non-melanoma cancers with great differences in observed response rates." (PMID 30463544, 2018). "Among the most significantly mutated genes was also BRAF, a well-known oncogene mutated in various cancers, such as melanoma (44%), CRC (10%), and lung adenocarcinoma (10%)." (PMID 29522538, 2018). "Inhibition of BRAF mutations using MAPK inhibitors suppresses glycolysis leading to temporarily suppression of melanoma growth, but also promotes metabolic switch to OXPHOS phenotype via induction of MITF and PGC1α expression." (PMID 30651927, 2018). "Recently, we reported that TRAB is efficacious on an osteosarcoma cisplatinum-resistant lung metastasis, a BRAF-V600E mutated melanoma and a gemcitabine (GEM)-resistant pancreatic cancer." (PMID 30126369, 2018). "It is worth noting that an association was also found between NLR and prognosis for melanoma patients treated by use of BRAF inhibitors." (PMID 30002656, 2018). "Malignant melanomas have active RAF-MEK-ERK signaling which can occur either through an activating mutation in BRAF (BRAFV600E) or through activation of signal transduction upstream of BRAF." (PMID 29481571, 2018). "Compared with BRAFWT and NRASWT melanoma, significantly higher DUSP6 expression was found in melanoma cells with BRAF and NRAS mutations." (PMID 30577494, 2018). "Our recent data indicate that NAMPT becomes the master regulator of NAD synthesis in BRAF-mutated melanoma cells that acquire resistance to BRAF inhibitors (BRAFi)." (PMID 29721178, 2018).
melanoma (continued). "It is found that 50–60% of melanomas formed by sunlight (UV) exposure, which causes BRAF mutation in vivo." (PMID 30544544, 2018). "For example, the human BRAF gene, which is one of the most frequently mutated genes in melanoma, shares almost 96% of identity with the corresponding gene in zebrafish." (PMID 30544544, 2018). "MHC class II restricted CD4+ T cells specific to the BRAF V600E mutation found in 40% of melanoma were isolated from a melanoma patient following a durable complete response to tumor infiltrating lymphocyte therapy." (PMID 30400835, 2018). "Targeted therapy of melanoma patients harboring BRAF (V600E) mutations with RAF and MEK inhibitors has markedly improved the outcome of this disease." (PMID 29880484, 2018). "Approximately 50% of all melanomas harbor BRAF mutations, and a number of agents are in development or have recently been approved to treat melanoma by targeting mutant BRAF." (PMID 30651933, 2018). "In the present work, we found that Gal-3 in melanocytes and melanoma cells decreased autophagy activity and it also regulated the cell fate after the treatment with the mutated BRAF inhibitor, vemurafenib (PLX-4032 or PLX)." (PMID 29581864, 2018). "In this study, we analyzed two human melanoma cell lines: MNT1 derived from pigmented pediatric melanoma and SkMel28 derived from white adult melanoma and we characterized them on the BRAF V600E variant, the most common mutation in melanoma." (PMID 29435180, 2018). "An example is the combined use of MEK inhibitors (MEKi) with BRAFi in melanoma harbouring BRAF V600E mutations." (PMID 30072489, 2018). "Intriguingly, the inhibition of E2F1 induced loss of cell viability of sensitive and BRAF inhibitor-resistant melanoma cells." (PMID 29743521, 2018). "Roche’s VE-BASKET trial of Zelboraf (vemurafenib), a phase 2 trial, enrolled patients with any type of non-melanoma cancer who had v-Raf murine sarcoma viral oncogene homolog B1 (BRAF) V600 mutations." (PMID 29764494, 2018). "As we observe the same effect in BRAFV600‐transformed fibroblasts and melanoma cells carrying the same mutation, oncogenic BRAF on its own is sufficient to prevent p66Shc activation." (PMID 29624862, 2018). "PLX8394 is being evaluated in phase I/IIa clinical trial for safety, pharmacokinetics and pharmacodynamics in patients with advanced BRAF mutated melanomas, thyroid carcinoma, colorectal cancer and NSCLC (NCT02428712)." (PMID 29455659, 2018). "Cell senescence and SASP were further investigated in human A375 (BRAFV600E mutation) and mice B16F10 (BRAF wild) melanoma cells using two more chemotherapeutic drugs, namely, PTX and dacarbazine." (PMID 29449532, 2018). "The introduction of combination BRAF and MEK inhibitor therapy has transformed treatment outcomes in patients with advanced-stage BRAF-mutated melanoma." (PMID 29148538, 2018). "The tumor suppressor gene PTEN is the third most frequently mutated gene in melanoma after BRAF and NRAS and promotes cell survival." (PMID 29946532, 2018). "For example, melanoma of unrelated patients converge on the classical BRAF-V600E mutation in 40% of cases." (PMID 29426936, 2018). "By probing The Cancer Genome Atlas (TCGA), we found significant upregulation of IGFBP2 mRNA and protein in melanoma harboring BRAF mutation compared to other mutational subtypes." (PMID 30143629, 2018). "Selective inhibitors of V600E BRAF mutated melanoma (vemurafenib, dabrafenib) were reported to improve the survival of patients harboring this specific mutation." (PMID 29330434, 2018). "This conclusion would fit with notions in human melanoma cells, which also bear the BRAF-V600E mutation and respond to a BRAF inhibitor with a reduced synthesis of CXCL8, thus resulting in anti-proliferative and anti-metastatic effects." (PMID 29977225, 2018). "Preliminary clinical reports evaluated the efficacy and safety of RT plus vemurafenib and dabrafenib in patients with BRAF V600E-mutated melanoma BMs." (PMID 29881714, 2018).
melanoma (continued). "Mutations in BRAF, a proto-oncogene, are associated with various types of cancers, especially melanoma." (PMID 30100909, 2018). "Cohorts B and C: patients with BRAF‐ or NRAS‐mutant melanoma who had either undergone surgical resection of high‐risk disease (cohort B) or were receiving or had received medical therapy for advanced disease (cohort C)." (PMID 30113761, 2018). "In the recent BRIM-8 study of adjuvant vemurafenib in BRAF-mutated melanoma, 16% of patients treated with adjuvant vemurafenib had BRAFi-cSCC or KA." (PMID 30154763, 2018). "We found that 38 out of 39 melanoma cell lines that have an activating BRAF mutation are fully resistant to necroptosis and have lost RIPK3 expression." (PMID 30157175, 2018). "We determined that gomesin peptides reduce viability in a panel of BRAF-mutated melanoma cell lines and demonstrated that HiGom has more profound antiproliferative properties than AgGom in the tested melanoma lines." (PMID 30068931, 2018). "BRAF mutations have previously been described in primary melanoma to be associated with the frequently observed arm- or chromosome-spanning gains of 7q40, which is consistent with our current results." (PMID 29991680, 2018). "In the current treatment of melanoma, only BRAF V600 mutations are regarded as being molecular markers applicable to treatment decision-making strategies." (PMID 30073150, 2018). "BRAF inhibitors such as vemurafenib and dabrafenib are effective in extending the progression free survival of BRAF-mutant melanomas which are present in 50% of melanomas and is associated with significantly higher incidence of CNS involvement." (PMID 30211117, 2018). "Another example is K63-linked ubiquitination at K578 in BRAF V600E, which serves as an oncogenic driver in melanoma, lung and colorectal cancer." (PMID 30335863, 2018). "BRAF inhibitors have proven beneficial in the management of tumors including BRAF-mutated melanomas." (PMID 29708404, 2018). "This is the case of melanomas carrying activating BRAF mutations, where BRAF inhibitors induce PGC1α, a master regulator of mitochondrial biogenesis, which in turn promotes oxidative metabolism." (PMID 30466459, 2018). "To avoid bias in this analysis, we selected only metastatic melanoma samples harboring a mutation in the V600 BRAF codon (n = 127), as all the melanoma cell lines in our previous analysis also carried this mutation." (PMID 30242167, 2018). "V600E mutations in BRAF occur commonly in cutaneous melanoma, and its targeted inhibitors, including vemurafenib, have been administered by the FDA as therapy for advanced melanoma patients with BRAF mutations." (PMID 30400954, 2018). "Approximately 50% of such tumors harbour the BRAF V600E mutation, which has also been observed in some melanomas where selective inhibitors have demonstrated a therapeutic role." (PMID 29951334, 2018). "The oncogenic BRAF mutations are found in approximately 8% of all human cancers, including 40–70% of melanoma, 36–53% of thyroid, and 5–22% of colorectal cancer (CRC) cases." (PMID 29755114, 2018). "The c.1799T>A mutation is the most common BRAF variant in melanoma and colorectal tumours, and so would be expected to be included in testing panels." (PMID 30030291, 2018). "For example, mutations in the BRAF gene are found in over 50% of melanomas, which made this cancer an attractive candidate for clinical trials on therapies that target BRAF-mutant tumors via the oncogenic variant gene product." (PMID 29854275, 2018). "Approximately 50-60% of melanomas have a mutation in the BRAF (v-Raf murine sarcoma viral oncogene homolog B protein) kinase." (PMID 30651927, 2018). "New generation of MEK inhibitors, such as trametinib (GSK1120212) and MEK162, have shown promising results in BRAF mutated melanoma and are being tested in combinations in phase III clinical trials (NCT02967692 and NCT01909453)." (PMID 30166456, 2018).